PITX1 (paired like homeodomain 1)
Diseases named in the same sentence as PITX1 in open-access papers (continued):
Sharing a sentence is not in itself a finding about the gene and the disease.
tumor (continued). "In conclusion, our data suggest a tumor suppressor role of PITX1 in OS progression." (PMID 36334221, 2023). "PITX1 plays a tumor suppressor role by downregulating the RAS pathway." (PMID 36882403, 2023). "Nude mice injected with tumor cells via tail intravenous injection to simulate tumor cell metastasis, showed a significant reduction in the number and size of lung metastases with the overexpression of PITX1 in tumor cells." (PMID 37841446, 2023). "The treatment of 5-AZA-CdR re-activated the activity of PITX1 regulon and may restore the tumor suppressive functions of PITX1." (PMID 36882403, 2023). "This article suggests that PITX1 may be an anti-apoptotic gene, and its overexpression can inhibit tumor cell apoptosis." (PMID 37841446, 2023). "Given PITX1 potent tumor-suppressive function, future investigations into drugs that inhibit PITX1 expression may be warranted." (PMID 37841446, 2023). "Several studies have identified PITX1 as a tumor marker for an unfavorable clinical course." (PMID 35267575, 2022). "PITX1 staining was evaluable for 15,011 tumor samples on TMA." (PMID 35267575, 2022). "Scenario 3 included PITX1 level, clinical tumor stage, pre-operative PSA level, and the “true” Gleason grade (which, however, can only be obtained from the prostatectomy specimens), while in scenario 4, the less reliable Gleason grade obtained from the biopsies were used." (PMID 35267575, 2022). "Additionally, PITX1 and PITX2 expression and methylation was associated with tumor-infiltrating lymphocytes (TILs)." (PMID 36204311, 2022). "PITX1 expression positively correlated with telomere staining intensity in PCa tumor samples." (PMID 35267575, 2022). "PITX1 acts as a tumor suppressor gene in various human cancers." (PMID 36204311, 2022). "To investigate whether PITX1 has multiple functions as a tumor suppressor gene, we generated A2058 (PITX1-A2058) and SKMEL28 (PITX1-SKMEL28) cells that transiently overexpress PITX1 or a control vector." (PMID 34526609, 2021). "Furthermore, in agreement with our result, PITX1 expression levels were positively correlated with SOX9 levels in tumor and normal skin tissues." (PMID 34526609, 2021). "The molecular mechanisms of the reduced expression of lincRNA C5orf66-AS1 and PITX1 in tumor tissue are incompletely understood and might be the result of epigenetic regulation." (PMID 29425237, 2018). "At least, PITX1 methylation status of the tumor could be one of the useful references for clinical decision making of invasive surgery." (PMID 29137437, 2017). "Hypermethylation of the PITX1 in ESCC correlated with tumor progression and advanced stage cancer, and may predict a poor prognosis." (PMID 29137437, 2017). "The reduced PITX1 expression observed in the malignant cases suggested that PITX1 may have a tumor-suppressing function." (PMID 24527083, 2014). "Unfortunately, animal models have not yet been used to investigate the role of PITX1 in tumorigenesis, and it remains unknown whether PITX1 deficiency in mice will promote or inhibit tumor growth." (PMID 37841446, 2023). "NSCLC cell line tumor progression is associated with an upregulation of miR-1204, which may be attributed to its direct binding to the 3’-UTR of PITX1, resulting in downregulated PITX1 expression and enhanced proliferation of NSCLC cells." (PMID 37841446, 2023). "Then, we examined whether LINC00662 could reverse PITX1-induced tumor suppression." (PMID 36334221, 2023). "Thus, PITX1 is considered to be a candidate tumor suppressor gene." (PMID 24527083, 2014). "Mechanistically, we found that PITX1 transcriptionally activates Phosphofructokinase platelet (PFKP), a key glycolytic enzyme, thereby enhancing glycolytic flux to promote tumor growth and metastatic capacity." (PMID 42065039, 2026).
tumor (continued). "We then investigated the correlation between PITX1 expression and clinicopathologic parameters in OC and CHS patients, including age, gender, tumor size, and tumor location." (PMID 40342824, 2025). "In the role of regulating epithelial biology, PITX1, along with SOX2 and the epidermal differentiation regulator TP63, function in a ternary transcriptional complex to maintain tumor-propagating cells in cutaneous squamous cell carcinoma (SCC)." (PMID 39480496, 2024). "Overexpressing KLF4 resulted in a decrease in PITX1 and Ki67 expression levels, and an increase in FLG2 staining intensity, inhibiting tumor growth." (PMID 37841446, 2023). "The activation of STAT1-related antiviral immunity and the restoration of tumor suppressive TF activities of HEYL and PITX1 would synergistically contribute to the anti-tumor effects of 5-AZA-CdR treatment." (PMID 36882403, 2023). "Conversely, knocking down KLF4 resulted in an increase in Ki67, PITX1, and SOX2 expression levels, and an increase in the malignancy of tumor tissue." (PMID 37841446, 2023). "Scenario 1 utilizes all available parameters after radical prostatectomy (pathological tumor stage, Gleason grade, lymph node, and surgical margin status, as well as pre-operative PSA level) and PITX1 level." (PMID 35267575, 2022). "It turned out that PITX1 expression contributed significantly, particularly in scenario 4, supporting its complementary role to PSA, tumor stage, and Gleason grade from the biopsy, i.e., to variables being available before prostatectomy." (PMID 35267575, 2022). "Moreover, the lack of PITX1 mRNA expression was associated with a higher tumor grade." (PMID 36204311, 2022). "The correlation between PITX1 and PITX2 expression or methylation and immune cell infiltration was evaluated using the tumor-immune system interaction database (TISIDB)." (PMID 36204311, 2022). "Low expression of PITX1 (p < 0.001) and PITX2 (p < 0.05) was observed in HNSC tumor tissues compared with normal tissues in unpaired specimens." (PMID 36204311, 2022). "PITX1 is a member of PITX family member that was considered as development related gene also and tumor suppressor in various carcinoma." (PMID 32830857, 2020). "The rationale for investigating PITX1 and lincRNA C5orf66-AS1 is strong, since both are lost in some tumor tissues." (PMID 29425237, 2018). "We restored PITX1 expression in ESCC cell lines and found that PITX1 functions as a tumor suppressor in ESCC progression both in vitro and in vivo." (PMID 29137437, 2017). "To further validate the correlation between PITX1 expression and the immune microenvironment, we utilized the CIBERSORT algorithm to analyze the proportions of tumor-infiltrating immune subgroups and generated a profile encompassing 20 different types of immune cells in CHS samples." (PMID 40342824, 2025). "Finally, we found that PITX1 expression levels are correlated with CHS grade, tumor differentiation and metastasis status in our patient cohort." (PMID 40342824, 2025). "Despite numerous studies of the tumor immune microenvironment, the effects of PITX1 on TICs and immune checkpoints in tumors have not been reported, and studies on the immune status of CHS remain limited." (PMID 40342824, 2025). "Furthermore, PITX1 has been shown to be overexpressed in cutaneous SCC and regulate the function of tumor-propagating cells." (PMID 39480496, 2024). "We did not observe spontaneous tumorigenesis in either healthy or wounded PITX1+ skin in the limited time scale we conducted these studies, suggesting that PITX1 expression alone or in combination with wounding is not sufficient for immediate tumor initiation." (PMID 39480496, 2024). "Although many studies have reported the involvement of PITX1 in tumor formation and progression, there is still a lack of relevant reviews to summarize these findings." (PMID 37841446, 2023).
tumor (continued). "In addition, methylation of PITX1 (exon 3) and C5orf66-AS1 lincRNA has also been strongly related to tumor localization, T class, HPV− and p16-negative cancers, and tumor grade." (PMID 36769317, 2023). "In the HPA data, compared with normal tissues, the expression of PKMYT1, ETF1, RECQL4, TUBB2B, and CDC6 in tumor tissues was remarkably upregulated, while the expression of TFRC and PITX1 was significantly downregulated (,ECT2, BUBB1B, and COCH were not included)." (PMID 33869220, 2021). "We propose that functional PITX1 complexes that regulate hTERT transcription are present in telomerase-negative tumor cells in which hTERT transcription is not detectable, but not in telomerase-positive tumor cells." (PMID 31404068, 2019). "Through PITX1-p120RasGAP signaling axis, PTP1B possesses tumor promoting effects in HCC." (PMID 29558404, 2018). "Finally, PITX1- and mock-transfected KYSE30 cells were used in a xenograft model of tumor formation in BALB/c nude mice." (PMID 29137437, 2017). "No PITX1 expression was detected in our pancreatic ACTH-secreting tumor sample." (PMID 40002253, 2025). "Furthermore, overexpression of PITX1 reduces the expression level of STAT3, promotes its degradation through the proteasome pathway, inhibits the expression of LINC00662, and thus suppresses EMT and tumor proliferation." (PMID 37841446, 2023). "Astonishingly, it has not been discussed whether PITX1 promotes angiogenesis in tumor tissue or wounds." (PMID 37841446, 2023). "Thus, thanks to the high sensitivity of Well-TEMP-seq, we can provide insights into the 5-AZA-CdR induced anti-tumor response of STAT1, HEYL, and PITX1 TFs activation in the early stage of treatment (e.g., in the first three days), which has not been unveiled before." (PMID 36882403, 2023). "Indeed, we observed higher Ki-67 values in tumor samples from patients with non-negative PITX1 protein expression, indicating higher proliferation of these tumors." (PMID 35267575, 2022). "Furthermore, PITX1 was strongly linked to the presence of ERG fusion: nearly 80% of ERG positive tumor samples (71.6% low and 6.9% high) but only 55% of ERG negative tumor samples (51.5% low and 3.3% high) (p < 0.0001) showed immune-histochemical PITX1 expression." (PMID 35267575, 2022). "In our study, we showed for the first time that the significant suppression of PITX1 is characteristic of smoking patients with HNSCC, and the level of PITX1 expression in the tumor tissue of smokers was lower than in nonsmoking patients." (PMID 38540309, 2024). "However, this scenario was not effective in our pancreatic ACTH-secreting tumor sample, where the absence of TBX19 and PITX1 overexpression points to alternative mechanisms driving the expression of POMC." (PMID 40002253, 2025). "PITX1 exon 3 and lincRNA C5orf66-AS1 methylation was also significantly correlated with tumor localization, T category, human papilloma virus (HPV)-negative and p16-negative tumors and tumor grade." (PMID 29425237, 2018). "According to the CPTAC data, the protein expression of PKMYT1, ETF1, ECT2, BUB1B, and RECQL4 in tumor tissues was significantly increased, while the expression of TFRC was significantly reduced, and the expression of COCH and TUBB2B did not change significantly (PITX1 and CDC6 were not included)." (PMID 33869220, 2021).
cancer (31 papers, 2014 to 2025). A tumor composed of atypical neoplastic, often pleomorphic cells that invade other tissues. "Our pan-cancer analysis revealed significant associations between PITX1 expression and immune infiltration across 39 cancer types, indicating its role in regulating TIC." (PMID 40342824, 2025). "High expression of PITX1 is associated with better patient survival, consistent with findings in other types of cancer." (PMID 36334221, 2023). "It showed that PITX1 positivity was strongly linked to all four deletions (p < 0.0001 each) in ERG-negative cancers, while this association was lost in ERG-positive cancers, most likely because of the general upregulation of PITX1 in this subset." (PMID 35267575, 2022). "CLEC4G and CpG site cg07274716 (associated with PITX1) distinguish cancer samples from normal with AUC 0.98 and 0.97 respectively." (PMID 31490960, 2019). "PITX1 has been shown to be associated with a variety of cancers." (PMID 40342824, 2025). "Differential expression of PITX1 has been reported in many malignant tumors and is associated with the survival prognosis of patients in several types of cancers, such as lung adenocarcinoma, osteosarcoma, esophageal squamous carcinoma, and head and neck squamous cell carcinoma." (PMID 34868397, 2021). "Several studies previously found that DNA hypermethylation of PITX1 is associated with the growth and progression of various cancers and may predict a poor prognosis." (PMID 32441304, 2020). "Moreover, understanding the interaction between PITX1 and physical activity will help to elaborate underlying biological mechanisms of cancer." (PMID 29484135, 2018). "Together with our data, dysregulation of PITX-1/p120RasGAP axis may be an important mechanism, in addition to mutation of Ras gene, explaining deregulated Ras signaling in cancer cells." (PMID 27752061, 2016). "In addition, lower PITX1 expression has been found in human cancer tissue samples and cell lines, and associated with poor survival in CRC patients." (PMID 26381143, 2015). "In other words, the loss of PITX1 may be associated with cancer cell proliferation." (PMID 29137437, 2017). "Pan-cancer analysis confirmed the differential expression of the PITX1 gene across multiple cancers, impacting survival prognosis, TIC patterns, and immune checkpoint regulation." (PMID 40342824, 2025). "Recent investigations have revealed the implication of dysregulated PITX1 expression in tumorigenesis, highlighting its involvement in cancer development." (PMID 37841446, 2023). "PITX1 is a critical transcription factor involved in suppressing the tumorigenicity of multiple human cancers, including colorectal cancer." (PMID 36882403, 2023). "This review aims to address this gap by providing a comprehensive overview of PITX1 in different cancer types, with a particular focus on its clinicopathological significance." (PMID 37841446, 2023). "The different cancer types with abnormal PITX1 expression are listed along with the corresponding prognosis." (PMID 37841446, 2023). "The phenomenon of both RAS oncogene overexpression and PITX1 knockdown within tumors yielding analogous cancer-promoting traits (such as proliferation, invasion, and migration) highlights the potential significance of RAS in this context." (PMID 37841446, 2023). "Collectively, this evidence suggests that PITX1 dysfunction induces activation of oncogenic pathways and promotes cancer development." (PMID 34526609, 2021). "The important role of PITX1 in the development of malignant tumor can be observed from cancer development, differential expression in cancer and related molecular mechanisms." (PMID 32830857, 2020).
cancer (continued). "Pitx1 is expressed in lung epithelia cells, but its expression level varies during cancer development and progression, indicating that homeobox genes are associated with differentiation and show unique expression patterns at different development stages." (PMID 32411685, 2020). "Collectively, this evidence suggests that PITX1 plays a crucial role in cancer development, though telomerase-dependent pathways." (PMID 31404068, 2019). "This confirms a more prominent role of PITX1 dysregulation in cancer development than previously thought." (PMID 29425237, 2018). "We therefore further investigated the regulation of PITX1 in order to understand the molecular mechanism of telomerase-dependent pathways in cancer development." (PMID 25643913, 2015). "Several studies have demonstrated reduced expression of PITX1 human cancer tissues and cell lines; PITX1 suppresses tumorigenicity by down-regulating the RAS pathway." (PMID 24968322, 2014). "Notably, low PITX1 expression was associated with poorer prognosis exclusively in HNSC, whereas 19 other cancer types demonstrated improved prognosis with low PITX1 expression." (PMID 40342824, 2025). "PITX1 has a regulatory effect on various functions in cancers." (PMID 40342824, 2025). "The biological function of PITX1 has been demonstrated in several types of cancer." (PMID 36334221, 2023). "Additionally, PITX1-positive cancers showed a higher Ki67 index pointing to accelerated cell proliferation, and this was independent of the Gleason grade." (PMID 35267575, 2022). "To understand whether the expression of PITX genes correlates with cancer, we evaluated PITX1, PITX2, and PITX3 mRNA expression in different human tumors (33 cancer types) and adjacent normal tissues using TCGA data." (PMID 36204311, 2022). "It has been shown that PITX1 regulates TERT also in cells of other cancer types." (PMID 35267575, 2022). "It was easy to find that PITX1 mRNA expression was different in various types of cancers." (PMID 34868397, 2021). "The differential expression of PITX1 mRNA has been observed in many types of cancer." (PMID 34868397, 2021). "Previous research has reported that PITX1 expression is decreased in numerous malignant tumors, which may be attributed to enrichment of binding gene promoters and regulation gene expression as a transcription factor." (PMID 34868397, 2021). "PITX1 is down-regulated in various malignant tumors and correlated with poor prognosis, may be because it enrichs in promoters of binding genes and regulates gene expression as a transcription factor." (PMID 32830857, 2020). "Interestingly, PITX1 expression is also decreased in several malignant tumors like gastric, colon and bladder cancer as well as HNSCC." (PMID 29425237, 2018). "This evidence suggests that PITX1 plays a crucial role in cancer development." (PMID 25643913, 2015). "PITX1 is a homeobox transcription factor with roles in both development and cancer." (PMID 24369427, 2014). "Furthermore, immune checkpoint analysis revealed a correlation between PITX1 expression and expression of pivotal immune checkpoint genes across various cancer types, indicating that PITX1 could serve as a promising diagnostic marker for immunotherapy." (PMID 40342824, 2025). "Additionally, it was established that circ-PITX1 induced cancer in GBM through targeting the miR-584-5p/KPNB1 axis, implying that circ-PITX1/miR-584-5p/KPNB1 could be used as a diagnostic marker for GBM patients." (PMID 35883576, 2022). "Moreover, downregulation of PITX1 is observed in various cancers including malignant melanoma." (PMID 34526609, 2021). "PITX1, SOX2, and TRP63 synergistically promote SCC self-renewal, cancer stem cells formation, and clonal expansion by opposing KLF4-dependent squamous cell differentiation." (PMID 37841446, 2023). "Paired-like homeodomain transcription factor 1 (PITX1) is involved in numerous biological processes, including cell growth, progression, and invasion in various malignant tumors." (PMID 34868397, 2021).